JAML (junction adhesion molecule like)
Diseases named in the same sentence as JAML in open-access papers (continued):
Sharing a sentence is not in itself a finding about the gene and the disease.
tumor (continued). "As expected, compared with the shNC or vector group, JAML knockdown significantly inhibited the xenograft tumor growth of A549 cells, and overexpression of JAML promoted the xenograft tumor growth of PC9 cells." (PMID 35672776, 2022). "JAML is involved in the proliferation and survival of T cells, as well as the production and release of cytokines and growth factors; thus, JAML regulates the sensitivity of tumor cells to relevant vaccines." (PMID 31715586, 2019). "PD-1 signaling within the NSCLC TME suppressed JAML expression-an effect reversible by PD-1 blockade-while the administration of a JAML agonist further enhanced the antitumor efficacy of PD-1 inhibitors in tumor-bearing mice." (PMID 41486351, 2026). "Notably, Joseph M. McGrawde and his team, using a mouse melanoma model, showed that combining an agonistic anti-JAML antibody with PD-1 therapy was more effective in suppressing tumor growth than either treatment alone." (PMID 40636111, 2025). "In recent years, the involvement of JAML in tumor biology has garnered increasing attention." (PMID 40636111, 2025). "Conversely, elevated JAML expression in tumor cells may contribute to tumor progression, underscoring the complex and context-dependent roles of JAML in cancer biology." (PMID 40636111, 2025). "However, significant concerns remain regarding the potential for agonistic anti-JAML antibodies to inadvertently stimulate tumor proliferation in malignancies with high JAML expression." (PMID 40636111, 2025). "Studies on JAML in cancer reveal its dual role, which depends on whether it is expressed in immune cells or tumor cells." (PMID 40636111, 2025). "The JAML protein has been found in neutrophils, monocytes, macrophages, tissue-resident γδ T cells, activated lymphoid γδ T cells, αβ T cells, renal podocytes, tumor cells, and APL cells." (PMID 40636111, 2025). "High immunogenic JAML expression limits tumor growth and enhances tumoricidal activity." (PMID 40636111, 2025). "The effects of JAML in vivo were studied in xenograft tumor models." (PMID 35672776, 2022). "JAML expression modulated tumor formation in xenograft transplantation experiments." (PMID 35672776, 2022). "We found that JAML may play a tumor-promoting role by activating the p38 signaling pathway." (PMID 33777731, 2021). "Studies have also shown that JAML activation enhances TLR1/2 expression on tissue-resident CD8+ T cells (CD8+ TRMs), which suppresses tumor progression and prolongs survival in tumor-bearing mice." (PMID 40636111, 2025). "JAML, an adhesion molecule on myeloid cells, interacts with JAM-C, promoting tumor cell extravasation and metastasis." (PMID 39055563, 2024). "This review summarizes the roles of JAML in both tumor and non-tumor diseases, emphasizing its functions in immune-related physiological processes." (PMID 40636111, 2025). "This review synthesizes current research on JAML, tracing its discovery and elucidating its roles in both tumor and non-tumor tissues, as well as its contributions to various inflammatory diseases and malignancies." (PMID 40636111, 2025). "In contrast to impaired antitumor immunity in the absence of JAML, treatment of tumor-bearing wild type (WT) mice with an anti-JAML agonistic antibody significantly limited tumor growth and extended median survival." (PMID 35480230, 2022). "Although studies on JAML under various pathological conditions are becoming more common, the relationship between JAML and tumor development has never been reported." (PMID 33777731, 2021). "Based on this initial characterization of JAML-CXADR-mediated costimulation of tissue-resident γδ T cells and the known roles of γδ T cells in antitumor immunity, the importance of JAML-CXADR interactions for γδ T cell responses within the tumor microenvironment (TME) was investigated." (PMID 35480230, 2022).
cancer (10 papers, 2021 to 2026). A tumor composed of atypical neoplastic, often pleomorphic cells that invade other tissues. "Among the top four upregulated DEGs, Chil3 is linked to immune function, whereas Fn1, JamL, and Ddit4 are associated with cancer." (PMID 40206211, 2025). "High expression of JAML in cancer tissues was associated with worse cell differentiation, local lymph node involvement, deep infiltration, and advanced stage." (PMID 33777731, 2021). "JAML knockdown promoted cancer cell proliferation, migration, invasion, and epithelial-mesenchymal transition (EMT) (all P < 0.01), accompanied by reduced stimulator of interferon genes (STING) phosphorylation (P < 0.01)." (PMID 41694334, 2026). "This underscores JAML’s significant potential as a therapeutic target and highlights its substantial value in cancer research." (PMID 40636111, 2025). "Immunohistochemistry revealed that 50% (25/50) of CRC patients exhibited high JAML expression, primarily localized in the cytoplasm and membranes of cancer cells, with minimal expression in stromal immune cells and negligible levels in adjacent normal tissues." (PMID 40636111, 2025). "Specific surface markers proposed to identify neutrophil subsets in cancer include CD101 and CD177, which are associated with cancer regression, and CD117, PDL1, CD170, LOX1, CD84 and JAML, which are associated with T cell immunosuppression and cancer progression." (PMID 34674757, 2021). "JAML was expressed in the cytoplasm and membrane of cancer cells." (PMID 33777731, 2021). "JAML (also known as AMICA1 in humans) is a member of the junctional adhesion molecule family, a class of molecules that facilitate tight junction assembly, regulate leukocyte-endothelial interactions, and have diverse roles in development, angiogenesis, inflammation, and cancer." (PMID 35480230, 2022). "Blocking JAML using antibodies or knocking out JAML significantly impaired the TEM activity of BMDCs, reducing the efficacy of DC-based cancer immunotherapy." (PMID 40636111, 2025). "Recently, the role of JAML was reported in LUAD, they found that JAML expression was decreased in LUAD and that JAML expression was correlated with immune infiltrates, but most of their conclusions were based on online databases, and the role of JAML may be very complex in cancers." (PMID 35672776, 2022). "Adhesion molecule interacting with CXADR antigen 1 (AMICA1), also known as Junction Adhesion Molecule Like (JAML), a recently identified member of the JAMs family, plays a critical role in mediating cancer development and immune cells transmigration." (PMID 35248033, 2022). "Although less well characterized, other γδ T cell costimulatory ligands such as JAML, CD100, LFA-1, and CD316 may also represent important targets for cancer immunotherapy." (PMID 35480230, 2022). "Given that LFA-1 and JAML function similarly as both adhesion and costimulatory molecules and studies demonstrating the antitumor activity of JAML agonism in vivo, it is interesting to speculate that agonist anti-LFA-1 antibodies may have a similar therapeutic effect for the treatment of cancer." (PMID 35480230, 2022).
infection (2 papers, 2024 to 2025). The state of being infected such as from the introduction of a foreign agent such as serum, vaccine, antigenic substance or organism. "The cell adhesion molecule coxsackievirus and adenovirus receptor (CAR) facilitates immune cell migration to infection/injury loci, and the CAR directly engages junctional adhesion molecule-like protein (JAML) on γδT17 cells, thereby inducing IL-17 release." (PMID 40806298, 2025).
kidney disease (2 papers, 2024 to 2025). "This phenomenon has also been observed in several pathogenic genes related to kidney disease, such as JAML and apolipoprotein L1." (PMID 38161229, 2024).
JAML also shares sentences with these, for which no sentence is quoted: lung adenocarcinoma (3 papers); lung carcinoma (3); adenocarcinoma (1); adenovirus infections (1); breast carcinoma (1); depression (1); diabetes (1); endometrial cancer (1); focal segmental glomerulosclerosis (1); gouty arthritis (1); Hypertension (1); kidney damage (1); lung diseases (1); Parkinson disease (1); squamous cell carcinoma (1); thyroid cancer (1); viral infection (1).